OASL (2'-5'-oligoadenylate synthetase like)
Diseases named in the same sentence as OASL in open-access papers (continued):
Sharing a sentence is not in itself a finding about the gene and the disease.
tumor (23 papers, 2009 to 2025). "The contrasting impact of OASL observed in certain tumor types is believed to be associated with their unique and specific molecular mechanisms." (PMID 39286258, 2024). "Moreover, we employed seven algorithms in bulk data to investigate the association of OASL expression and immune cell infiltration within tumor immune microenvironment (TIME) and ultimately validated at single-cell transcriptome level." (PMID 39286258, 2024). "In addition, the PML‐NB‐associated proteins, ISG20, OAS3, OAS1, and OASL were found to be upregulated and are considered to be tumour suppressors involved in promoting DNA cleavage, nuclear condensation, and apoptosis." (PMID 36579897, 2023). "Additionally, we delved into the types of genetic variations in OASL, especially those mutations affecting transcription factors or regulatory regions, which could contribute to tumor heterogeneity." (PMID 39286258, 2024). "Consequently, conclude that OASL is closely linked to the degree of tumor malignancy." (PMID 39286258, 2024). "Critically, OXA effectively induced ICD in tumor-bearing mice, and OASL knockdown further potentiated this effect." (PMID 41271618, 2025). "The weight of tumor-bearing tissue was significantly lower in the sh-OASL group than that in the sh-NC OASL group." (PMID 41271618, 2025). "Genes implicated in the modulation of tumor microenvironment and immunomodulation include CLIC5, RSAD2 and OASL." (PMID 40312750, 2025). "Tumor volume decreased in the sh-OASL group compared to the sh-NC group, and the OXA+sh-OASL group exhibited a statistically significant reduction (P < 0.05)." (PMID 41271618, 2025). "OASL facilitated immune evasion through decreasing expression of MHC-I on the surface of PDAC tumor cells and impeding activation of CD8+T cells." (PMID 39990208, 2025). "The weight of the tumor-bearing tissue was significantly lower in the sh-OASL group than that in the sh-NC + OASL group (P < 0.01)." (PMID 41271618, 2025). "In conclusion, the mouse tumor-bearing model verified that knockdown of OASL enhanced the activation of the cGAS-STING signaling pathway and enhanced OXA-induced ICD in GC cells,thus increasing the sensitivity of OXAchemotherapy." (PMID 41271618, 2025). "It’s easily inferred that tumor cell itself induces PD-L1 overexpression by upregulating OASL, affecting T cell dysfunction and leading to exhaustion." (PMID 39286258, 2024). "In summary, high expression of OASL in tumor tissues activates immune responses such as IFN-γ, STAT1, IL6_JAK_STAT3 signaling, which in turn promotes the expression of PD-L1." (PMID 39286258, 2024). "To evaluate patient survival, we applied COX and Log-rank regression models for an initial examination of the association between OASL expression and prognostic factors such as DFI, DSS, OS, and PFI across 33 tumor types." (PMID 39286258, 2024). "During our analysis of the enrichment of immune-regulatory pathways, we observed positive correlation between OASL expression and classic anti-tumor immune pathways across various tumors." (PMID 39286258, 2024). "Firstly, we compared the mRNA expression of OASL in normal and tumor tissues using the TCGA database, revealing high expression in ESCA, HNSC, KIRC, KIRP, PAAD, PCPG, and UCEC." (PMID 39286258, 2024). "First, the biological functions of MET, OAS1, and OASL such as their interactions with immune cells in tumor microenvironment need to be explored in vitro experiments." (PMID 33869254, 2021). "Meanwhile, OASL expression was markedly elevated in tumor specimens in the GSE15471 (p = 1.328e-05) and GSE62452 datasets (p = 7.153e-10)." (PMID 33869254, 2021). "The results indicated that, as NOL12, PABPC1L, RNASE2, RPL22L1, and OASL expression increased, tumor grade, AJCC stage, T stage, and M stage in KIRC patients increased." (PMID 33229623, 2020).
tumor (continued). "This suggests that elevated OASL expression may contribute to an immunosuppressive state especially in later stages of anti-tumor immunity process, such as during immune cell infiltration, T cell recognition, and cell killing." (PMID 39286258, 2024). "The observed positive correlation between OASL and PD-L1 suggests that targeting OASL could enhance the efficacy of PD-1/PD-L1 inhibitors, synergizing tumor immune-targeted therapy." (PMID 39286258, 2024). "However, the anti-tumor immunity of OASL has rarely been reported." (PMID 39990208, 2025). "Hence, we further investigated the expression source of OASL in tumor as an ISG." (PMID 39286258, 2024). "Thus, MET, OAS1, and OASL were distinctly correlated to tumor immune microenvironment." (PMID 33869254, 2021). "Interestingly, neutrophils exhibited the highest correlation with OAS members (cor = 0.268 in OAS1; cor = 0.42 in OAS2; cor = 0.371 in OAS3; cor = 0.332 in OASL), highlighting the key role of OAS members associated with neutrophils in tumor immune infiltrating cells." (PMID 32560641, 2020). "The orthotopic PDAC models were constructed to evaluate the effects of OASL-knockdown on CD8+ T cells infiltration and tumor growth in vivo." (PMID 39990208, 2025). "The expression of MHC-I on the surface of tumor cells was increased by OASL-knockdown, while overexpression of OASL can significantly reduce the expression of MHC-I on the surface of tumor cells." (PMID 39990208, 2025). "Our study mainly focused on that OASL facilitates the degradation of MHC-I and slack of anti-tumor adaptive immunity derived from CD8+T cells through NBR1-mediated autophagy-lysosomal degradation." (PMID 39990208, 2025). "It is suggested that over expressed OASL is related to cancer cells themselves in the TIME, leading to immune response of tumor cells." (PMID 39286258, 2024). "As expected, the expression of IL20RB, MET, OASL, and PLAU in tumor tissues was significantly higher than that in normal tissues." (PMID 34335699, 2021). "NOL12, PABPC1L, RNASE2, RPL22L1, OASL, and YBX3 expression were significantly positively correlated with tumor grade and AJCC stage, while RBM47 expression was negatively correlated with tumor grade and AJCC stage." (PMID 33229623, 2020). "IFI30, OASL, and a HSP70 were found to be upregulated in tumor samples as observed in the proteomic analysis." (PMID 30651403, 2019). "An interferon gene signature was also present in the profiles derived from the tumor epithelium of the ER-positive tumors (e.g., STAT1, IFIT1, IFIH1, IFI27, ISG15, OAS1, OAS3, OASL) and ER-negative tumors (e.g., HLA-DQA1 and HLA-DQB1)." (PMID 19225562, 2009). "Unlike these tumor-intrinsic adaptations, we demonstrate that OASL impairs ICD by directly binding cGAS and suppressing cGAS-STING signaling pathway, thereby inhibiting dendritic cell maturation and CD8+T-cell infiltration." (PMID 41271618, 2025). "Our study demonstrated that OASL-knockdown increased MHC-I levels by inhibiting NBR1-mediated autophagy-lysosomal degradation in PDAC, contributing to the infiltration of CD8+T cells and tumor suppression." (PMID 39990208, 2025). "Notably, OASL-knockdown leads to a significant increase in CD8+ T cell infiltration and slows tumor growth in vivo." (PMID 39990208, 2025). "Additionally, OASL regulates immune checkpoint ligand such as programmed death ligand 1 (PD-L1), through IFN-γ/STAT1 and IL-6/JAK/STAT3 pathways in tumor cells." (PMID 39286258, 2024). "Results showed that the expressions of OAS2, OAS3, and OASL had significant negative correlations with tumor purity in BLCA." (PMID 36162993, 2022). "OASL, EGR1, and BMP2 were significantly downregulated in tumor in GSE13861." (PMID 30134903, 2018). "Therefore, we propose that PDAC patients with high expression of OASL may respond better to a combination therapy of CQ and dual ICB, suggesting a new direction for anti-tumor therapy development." (PMID 39990208, 2025).
cancer (18 papers, 2014 to 2025). A tumor composed of atypical neoplastic, often pleomorphic cells that invade other tissues. "We found that OASL is overexpressed in several cancer types and is associated with poor prognosis." (PMID 39286258, 2024). "This study comprehensively investigated the expression and prognosis of OASL across various cancers." (PMID 39286258, 2024). "For instance, OASL expression indicates worse prognosis in cancers such as PAAD, KIRC, LGG, THYM, and UVM, but suggests better function in BLCA and SKCM, aligning with previous findings." (PMID 39286258, 2024). "In our study, we systematically investigated the OASL gene in pan-cancer through the integration of multi-omics data and bioinformatics analysis." (PMID 39286258, 2024). "Modulation of OASL could be an alternative strategy for improving drug efficacy during cancer treatment." (PMID 41271618, 2025). "A recent study found that the correlation between OASL and cancer has been gradually confirmed, which may participate in the development of breast cancer, pancreatic cancer, and cervical cancer, and is closely related to prognosis." (PMID 41271618, 2025). "This highlights the heterogeneity in OASL at the CNV level among these cancers." (PMID 39286258, 2024). "To gain a deeper insight into OASL’s function in various cancers, we examined its expression patterns using The Cancer Genome Atlas (TCGA) database, which encompasses detailed descriptions on 33 different cancer types." (PMID 39286258, 2024). "Multi-omics analysis reveals OASL as a prognostic and immunological biomarker in pan-cancer." (PMID 39286258, 2024). "Moreover, we examined the influence of OASL on genomic stability and genetic variability in various cancers." (PMID 39286258, 2024). "In summary, OASL remains a complex and active role in cancer research." (PMID 39286258, 2024). "A systemic pan-cancer study of OASL needs to be illustrated." (PMID 39286258, 2024). "Furthermore, DDX58 protein levels were increased and has been seen to play a role alongside OASL, whereby downregulation of these proteins is observed to enhance cancer cell motility and invasion." (PMID 36579897, 2023). "The regulation of OASL may be an alternative strategy to improve drug efficacy during cancer therapies." (PMID 36162993, 2022). "Notably, OASL exhibits diverse and even opposite roles in different cancers." (PMID 39286258, 2024). "However, the roles of IFI27 and OASL in CDDP-R cancer cells await future investigation." (PMID 37174688, 2023). "Moreover, OASL was considerably related to cancer proliferation." (PMID 32560641, 2020). "In our final analysis, we delved into the relationship between OASL expression and the TME across various cancers." (PMID 39286258, 2024). "Our study comprehensively explored OASL’s role in cancer and its interaction with the TIME opens new avenues for potentially leading to more effective and personalized cancer treatments." (PMID 39286258, 2024). "Based on these results, we conclude there is a certain correlation between OASL and the TIME, which has been validated at both the pan-cancer and PAAD levels." (PMID 39286258, 2024). "The RT-qPCR results confirmed that the expressions of ISG15, IFI27, and OASL increased significantly in KU55933-treated CDDP-R and parent cancer cells." (PMID 37174688, 2023). "On the other hand, the expression levels of ISG15, IFI27, OASL, ISG20, and DDX58 were lower in CDDP-R cancer cells than in parent cancer cells, which were consistent with the transcriptome profiling data." (PMID 37174688, 2023). "The results showed that high expressions of ISG15, IFI27, OASL, CCL5, ISG20, IFIT3, and other 21 ISGs were significantly correlated with improved OS rates in cancer patients receiving ICB therapy." (PMID 37174688, 2023). "Despite increasing reports has been put on OASL’s role in cancer, there is currently no systematic study on OASL in pan-cancer, especially regarding aspects related to TIME." (PMID 39286258, 2024).
cancer (continued). "Interestingly, some of the factors such as a xylulokinase homologue (XYLB), the 2′-5′-oligoadenylate synthetase like (OASL) and the interferon-induced protein (IFI44) have not been so far linked to cancer and may represent markers of aneuploidy that are not linked to malignancy." (PMID 24548329, 2014).
bacterial infections (6 papers, 2017 to 2025). "OASL has considerable discriminatory power in differentiating between viral and bacterial infections." (PMID 32714913, 2020). "OASL is known to possess antiviral mediated roles and has been recently shown to have a role in antiviral innate immunity, and it has been previously studied in the context of differentiating viral from bacterial infections." (PMID 35186993, 2022). "In addition, OASL was included by previous panels for discriminating viral and bacterial infections." (PMID 32714913, 2020). "Intracellular bacteria are able to activate the cytosolic DNA sensing pathway, however the role of OASL during bacterial infection is largely unknown." (PMID 28580319, 2017). "Still, several differentially expressed genes identified in our study overlapped with those frequently appearing in other published signatures differentiating bacterial from non-bacterial infections developed in immunocompetent children, including IFI27, OASL, and ISG15." (PMID 40806258, 2025).
cardiovascular disease (2 papers, 2021 to 2022). "In addition, other miRNAs that were up-regulated in OASL-KD HUVECs may participate in cardiovascular disease, which suggests a potential use as markers of endothelial dysfunction." (PMID 36333342, 2022).
renal disorders (2 papers, 2020 to 2021). "However, patients with active SLE who had renal disorders showed upregulated OASL in PBMCs and CD19+ B cells compared to that in patients without clinical manifestations." (PMID 34149799, 2021). "Active SLE patients with renal disorders showed higher OAS2 and OASL expression in PBMCs, OAS3 and OASL expression in CD19+ B cells, and OAS3 expression in CD4+ T cells than patients without the symptoms (P<0.05)." (PMID 32321151, 2020).
OASL also shares sentences with these, for which no sentence is quoted: discoid lupus erythematosus (2 papers); H1N1 virus infection (2); melanoma (2); AIDS (1); Alzheimer disease (1); asthma (1); Autoimmunity (1); avian influenza (1); bladder cancer (1); Cerebral ischemia (1); chronic hepatitis C (1); chronic obstructive pulmonary disease (1); colon cancer (1); congenital heart disease (1); endothelial dysfunction (1); esophageal cancer (1); Hepatitis (1); human papillomavirus infection (1); hyperlipidemia (1); Hypertension (1); infectious disease (1); ischemia (1); juvenile dermatomyositis (1); kidney cancer (1); lepromatous leprosy (1); liver diseases (1); lung disease (1); lung fibrosis (1); measles (1); metastatic tumor (1).
A further 10 diseases each share a sentence with OASL in 1 paper.